PLOD3 (procollagen-lysine,2-oxoglutarate 5-dioxygenase 3)
Diseases named in the same sentence as PLOD3 in open-access papers (continued):
Sharing a sentence is not in itself a finding about the gene and the disease.
tumor (continued). "The Sangerbox tool was used to obtain the immune maps that could show the relation between the expression of PLOD3 and immune cell infiltration in a tumor microenvironment (TME)." (PMID 34576068, 2021). "Furthermore, a recent study has indicated that PLOD3 knockdown can suppress tumor growth in the liver of spontaneous HCC mice." (PMID 33014843, 2020). "Collectively, these findings suggest that PLOD3 is correlated with tumor growth." (PMID 30770789, 2019). "In summary, the PLOD3 siRNA used in this study are potent tools to modulate PLOD3 expression and they might ultimately be developed into attractive anti-tumor therapeutics." (PMID 30770789, 2019). "In HCC, tumor genes such as procollagen-lysine, 2-oxoglutarate 5-dioxygenase 3 (PLOD3), and splicing factor 3b subunit 4 (SF3B4) are overexpressed in HCC tumor tissues compared with adjacent tissues, and knocking down their expression levels can effective suppress tumor invasion." (PMID 31156698, 2019). "In the in vitro study, PLOD3 knockdown suppressed tumor growth and progression." (PMID 29644003, 2018). "However, the opposite effect was observed with PLOD3 knockdown, with lower tumor volume and weight." (PMID 40133271, 2025). "Therefore, our findings suggest that a subset of TNBC patients with more TLS or lower expression of PML and PLOD3 in tumor will be the group who may benefit more from camrelizumab combined with apatinib and eribulin." (PMID 35641481, 2022). "In addition, we also extracted cell lysates from these tumors and confirmed PLOD3 depletion in these PLOD3 shRNA infected cells, suggesting that the decreased tumor growth may derive from PLOD3 depletion." (PMID 35835735, 2022). "In addition, the high PLOD3 expression group had a higher TIDE score and a lower tumor mutation burden and microsatellite instability, indicating that patients with high PLOD3 expression may be resistant to immunotherapy." (PMID 34646265, 2021). "Next, immunohistochemistry (IHC) showed that PLOD3 was upregulated in CRC tissues, as reflected by the increased H-scores obtained, which is consistent with the Clinical Proteomic Tumor Analysis Consortium (CPTAC) data." (PMID 40133271, 2025). "We found that PLOD3 is overexpressed in CRC due to promoter hypomethylation, and its increased expression is positively correlated with tumor stage, lymph node metastasis, and distant metastasis." (PMID 40133271, 2025). "Thus far, the mechanism of tumor cell migration and invasion involving PLOD3 is unknown." (PMID 38184566, 2024). "In accordance with that, knockdown of PLOD3 inhibited HIF-1α accumulation via the ERK signaling pathway under hypoxia, suggesting that PLOD3 had the potential to regulate the tumor microenvironment." (PMID 34239923, 2021). "What’s more, we performed immunohistochemistry (IHC) staining for PLOD3 in 160 paired CRC specimens and corresponding adjacent non-tumor tissues." (PMID 34646265, 2021). "Functional analyses revealed that PLOD3 interacts with STAT3, thereby expressing matrix metalloproteinases (MMP-2 and MMP-9) and with urokinase plasminogen activator (uPA) to enhance tumor metastasis." (PMID 30442941, 2018). "Tumor aggressiveness stimulated by HIF-1α has been found to rely on collagen remodeling enzymes, including PLOD2, and the prolyl hydroxylases, but PLOD3 is poorly studied." (PMID 29644003, 2018). "Next, we used ImmuCellAI to evaluate the immune infiltration score and the abundance of 24 immune cells from tumor tissues, and then calculated the multiple and single correlation coefficients of ADAM12, MMP1, SERPINE1, PLOD3, and P4HA3 with mRNA expression and immune infiltration score." (PMID 34121340, 2021). "In a mouse xenograft model, PLOD3 knockdown promoted radiation-induced tumor growth inhibition, without side effects." (PMID 30770789, 2019).
tumor (continued). "Second, although we showed that PLOD3 can be secreted by CRC cells and that PLOD3 promotes CRC cell migration and invasion both in vitro and in vivo, the mechanisms by which PLOD3 is secreted extracellularly to promote tumor progression need to be further investigated." (PMID 40133271, 2025). "Moreover, the genes involved in two tumor-promoting pathways, including gluconeogenesis and TGF-beta signaling in epithelial-mesenchymal transition (EMT), were significantly enriched in those positively correlated with PLOD3 (FDR < 0.05)." (PMID 34239923, 2021). "Moreover, negative correlations were observed between PLOD3 expression and multiple immune related genes, suggesting that PLOD3 plays a negative role in regulating tumor immunology." (PMID 34646265, 2021). "In particular, the staining shows PLOD3 expression in the stromal cell populations of the TME, not of the tumor cells themselves." (PMID 34576068, 2021).
connective tissue disorder (14 papers, 2014 to 2026). A disease involving the connective tissue. "BACKGROUND: BCARD syndrome is a rare complex connective tissue disorder associated with variants in the PLOD3 gene, presenting with musculoskeletal, vascular, and sensory deficits." (PMID 41827019, 2026). "To date, data have been accumulating on the associations of PLOD3 variants with connective tissue disease and its vascular complications as well as familial and sporadic vascular aneurysms in some populations." (PMID 39125885, 2024). "PLOD3 is found on c7q22.1 and homozygous mutations in it cause a rarely reported connective tissue disease that has some overlap in features with Sticklers syndrome, Ehlers Danlos syndrome and epidermolysis bullosa." (PMID 37686358, 2023). "Compound heterozygous or homozygous variants in PLOD3 cause a systemic connective tissue disorder in humans." (PMID 37426526, 2023). "Previous studies have shown that the mutation of PLOD3 can lead to disorders of connective tissue disease and other diseases." (PMID 34576068, 2021). "We also suggest that it is likely that mutations of COLGALT1 would cause connective tissue disorders in humans, similar to the patient with a defect in PLOD3 expression whose phenotype included bone fragility and contractures." (PMID 31101663, 2019). "Recently, mutations in the human LH3 gene (PLOD3) were shown to cause a severe connective tissue disorder with features that overlap with a number of collagen disorders." (PMID 25419660, 2014). "Indeed, connective tissue disorders associated with PLOD3 are typically autosomal recessive, and heterozygous parents of affected cases are reported to be asymptomatic." (PMID 36403858, 2022). "It has been shown that PLOD3 mutations are associated with the connective tissue disorder." (PMID 30003082, 2018). "Studies in human patients with connective tissue disorders and heterozygous PLOD3 knock-out mice have shown that even a moderate reduction in PLOD3 levels leads to connective tissue abnormalities accompanied by developmental defects." (PMID 39975904, 2025). "The role for LH3 in collagen α1α1α2(I) and collagen α1α1α1(III) glycosylation is consistent with the identification of PLOD3 pathogenic variants in individuals with connective tissue disorders." (PMID 36403858, 2022). "The expression of procollagen-lysine, 2-oxoglutarate 5-dioxygenase 3 (PLOD3) is essential for the biosynthesis of collagen and gene mutations thereof, and are related to disorders of the connective tissue." (PMID 34576068, 2021).
cardiovascular diseases (1 paper, 2023). "Genetic analysis targeting 404 different genes involved in inheritable cardiovascular diseases identified a heterozygous stop-gain variant in PLOD3, which encodes LH3." (PMID 37426526, 2023).
PLOD3 also shares sentences with these, for which no sentence is quoted: genetic disease (2 papers); idiopathic pulmonary fibrosis (2); intracranial hemorrhage (2); Obesity (2); osteogenesis imperfecta (2); renal cell carcinoma (2); adenocarcinoma (1); aneurysm (1); basal cell carcinoma (1); Becker muscular dystrophy (1); bladder cancer (1); cataract (1); cholestasis (1); Cirrhosis (1); colorectal tumor (1); cyst (1); diabetes (1); Ehlers-Danlos syndrome (1); esophageal adenocarcinoma (1); fibrosarcoma (1); fibrosis (1); hemorrhage (1); hepatitis C (1); ichthyosis (1); Insulin resistance (1); intracerebral hemorrhage (1); kidney tumor (1); large cell lung carcinoma (1); nephrotic syndrome (1); neuroblastoma (1).
A further 5 diseases each share a sentence with PLOD3 in 1 paper.